KCNN2 (potassium calcium-activated channel subfamily N member 2)
Description:
Small conductance calcium-activated potassium channel that mediates the voltage-independent transmembrane transfer of potassium across the cell membrane through a constitutive interaction with calmodulin which binds the intracellular calcium allowing its opening. The current is characterized by a voltage-independent activation, an intracellular calcium concentration increase-dependent activation and a single-channel conductance of about 3 picosiemens. Also presents an inwardly rectifying current, thus reducing its already small outward conductance of potassium ions, which is particularly the case when the membrane potential displays positive values, above + 20 mV. The inward rectification could be due to a blockade of the outward current by intracellular divalent cations such as calcium and magnesium and could also be due to an intrinsic property of the channel pore, independent of intracellular divalent ions. There are three positively charged amino acids in the S6 transmembrane domain, close to the pore, that collectively control the conductance and rectification through an electrostatic mechanism. Additionally, electrostatic contributions from these residues also play an important role in determining the intrinsic open probability of the channel in the absence of calcium, affecting the apparent calcium affinity for activation. Forms an heteromeric complex with calmodulin, which is constitutively associated in a calcium-independent manner. Channel opening is triggered when calcium binds the calmodulin resulting in a rotary movement leading to the formation of the dimeric complex to open the gate (By similarity). Plays a role in the repolarization phase of cardiac action potential.
Synonyms: SK2; SKCa 2; SKCa2; KCa2.2; hSK2; DYT34; NEDMAB
Tractability: Small molecule: a structure with a bound ligand is known; a high-quality ligand is known; it belongs to a druggable protein family. Antibody: its Gene Ontology location is reachable by antibodies, with high confidence; UniProt predicts a signal peptide or a membrane-spanning region. PROTAC: ubiquitination databases record sites on it; a small molecule that binds it is known.
Target class: Voltage-gated ion channel; Ion channel; Calcium-activated potassium channel; Potassium channels
Safety:
Unwanted effects reported when the protein is acted on. In parentheses: how it was acted on, where the effect was seen, and who reports it.
ataxia (activation, acute dosing; central nervous system, cardiovascular; source: Lynch et al. (2017))
convulsions (inhibition, acute dosing; central nervous system, cardiovascular; source: Lynch et al. (2017))
decreased convulsions (activation, acute dosing; central nervous system, cardiovascular; source: Lynch et al. (2017))
decreased locomotor activity (activation, acute dosing; central nervous system, cardiovascular; source: Lynch et al. (2017))
increased atrial refractory period (inhibition, acute dosing; central nervous system, cardiovascular; source: Lynch et al. (2017))
neurotoxicity (inhibition, acute dosing; central nervous system, cardiovascular; source: Lynch et al. (2017))
Gene: Protein-coding gene on chromosome 5 (114,055,926 to 114,496,500, forward strand). Ensembl gene ENSG00000080709.
Subcellular location: Membrane; Cytoplasm, myofibril, sarcomere, Z line
Subcellular location (Human Protein Atlas): Nucleoplasm; Plasma membrane
Pathways (Reactome):
Neuronal System: Ca2+ activated K+ channels
Sensory Perception: Acetylcholine inhibits contraction of outer hair cells
Gene Ontology:
Molecular function: alpha-actinin binding; calcium-activated potassium channel activity; inward rectifier potassium channel activity; protein binding; protein domain specific binding; protein homodimerization activity; small conductance calcium-activated potassium channel activity; calmodulin binding
Biological process: potassium ion transmembrane transport; regulation of potassium ion transmembrane transport; membrane repolarization during atrial cardiac muscle cell action potential; potassium ion transport
Cellular component: cell surface; plasma membrane; dendritic spine; membrane; neuronal cell body; Z disc
Genetic constraint (gnomAD): Loss-of-function variants: 18 observed, 40.37 expected, observed/expected ratio (o/e) 0.45, 90% interval 0.31 to 0.66. The upper end of that interval is the gene's LOEUF score, 0.66, which puts it in group 2 of 6, group 1 being the genes least tolerant of losing a copy. Missense variants: 600 observed, 715.17 expected, observed/expected ratio (o/e) 0.84, 90% interval 0.78 to 0.9. Synonymous variants: 328 observed, 275.17 expected, observed/expected ratio (o/e) 1.19, 90% interval 1.09 to 1.31.
Homologues: Orthologues: chimpanzee KCNN2 (99% identical), macaque KCNN2 (99% identical), rat Kcnn2 (98% identical), pig KCNN2 (97% identical), guinea pig KCNN2 (97% identical), tropical clawed frog kcnn2 (77% identical), mouse Kcnn2 (72% identical), rabbit KCNN2 (68% identical), zebrafish kcnn2 (61% identical), Drosophila melanogaster SK (46% identical), Caenorhabditis elegans kcnl-2 (32% identical), Caenorhabditis elegans kcnl-1 (27% identical), and 2 more. Paralogues in human: KCNN3 (61% identical), KCNN1 (48% identical), KCNN4 (24% identical).